EEF1A2 (eukaryotic translation elongation factor 1 alpha 2)
Description:
Translation elongation factor that catalyzes the GTP-dependent binding of aminoacyl-tRNA (aa-tRNA) to the A-site of ribosomes during the elongation phase of protein synthesis. Base pairing between the mRNA codon and the aa-tRNA anticodon promotes GTP hydrolysis, releasing the aa-tRNA from EEF1A1 and allowing its accommodation into the ribosome (By similarity). The growing protein chain is subsequently transferred from the P-site peptidyl tRNA to the A-site aa-tRNA, extending it by one amino acid through ribosome-catalyzed peptide bond formation (By similarity).
Synonyms: EF-1-alpha-2; EEF1AL; STN; HS1; DEE33; EF1A; EIEE33; MRD38; STNL
Tractability: Small molecule: a drug acting on it is in phase 2 or 3 trials. PROTAC: ubiquitination databases record sites on it; its protein half-life has been measured; a small molecule that binds it is known.
Chemical probes: PD081089
Gene: Protein-coding gene on chromosome 20 (63,477,488 to 63,500,533, reverse strand). Ensembl gene ENSG00000101210.
Subcellular location: Endoplasmic reticulum membrane
Subcellular location (Human Protein Atlas): Cytosol
Pathways (Reactome):
Metabolism of proteins: Eukaryotic Translation Elongation
Gene Ontology:
Molecular function: protein binding; protein kinase binding; GTPase activity; translation elongation factor activity; translation factor activity, RNA binding; GTP binding
Biological process: positive regulation of lipid kinase activity; regulation of chaperone-mediated autophagy; translation; translational elongation
Cellular component: cytoplasm; endoplasmic reticulum membrane; nucleus; cytoplasmic side of lysosomal membrane; eukaryotic translation elongation factor 1 complex; synapse
Genetic constraint (gnomAD): Loss-of-function variants: 5 observed, 33.49 expected, observed/expected ratio (o/e) 0.15, 90% interval 0.077 to 0.31. The upper end of that interval is the gene's LOEUF score, 0.31, which puts it in group 1 of 6, group 1 being the genes least tolerant of losing a copy. Missense variants: 218 observed, 637.15 expected, observed/expected ratio (o/e) 0.34, 90% interval 0.31 to 0.38. Synonymous variants: 287 observed, 286.26 expected, observed/expected ratio (o/e) 1, 90% interval 0.91 to 1.11.
Gene-disease validity (ClinGen):
ClinGen rates the evidence that EEF1A2 causes each of these diseases.
complex neurodevelopmental disorder (autosomal dominant): Definitive. A disorder that involves more than one phenotype associated with the central nervous system, including but not limited to intellectual disability, autism, and seizures (epilepsy).
Homologues: Orthologues: chimpanzee EEF1A2 (100% identical), guinea pig EEF1A2 (100% identical), macaque EEF1A2 (99% identical), mouse Eef1a2 (99% identical), rat Eef1a2 (99% identical), tropical clawed frog eef1a2 (98% identical), dog EEF1A2 (96% identical), zebrafish eef1a2 (94% identical), pig EEF1A2 (94% identical), Caenorhabditis elegans tufm-2 (24% identical), Caenorhabditis elegans eif-2gamma (22% identical), Drosophila melanogaster mEFTu2 (22% identical), and 1 more. Paralogues in human: EEF1A1 (92% identical), GSPT1 (35% identical), GSPT2 (34% identical), HBS1L (30% identical), TUFM (29% identical), EIF2S3B (25% identical), EIF2S3 (25% identical), EFL1 (24% identical), EIF5B (24% identical), GTPBP1 (24% identical), GTPBP2 (24% identical), EEF2 (23% identical), and 6 more.
Diseases named in the same sentence as EEF1A2 in open-access papers:
EEF1A2 is named in the same sentence as 154 diseases in open-access papers, as found by Europe PMC text mining. Sharing a sentence is not in itself a finding about the gene and the disease. The quoted sentences say what the papers report.
breast carcinoma (61 papers, 2005 to 2025). "It is worth to underline that with respect to 80% of pancreatic cancers, only 30%-60% of breast cancer showed overexpression of eEF1A2, underlying the heterogeneity of eEF1A2 expression in breast cancers." (PMID 31220107, 2019). "EEF1A2 expression is reported to be associated with good prognosis in breast cancer and non-small cell lung cancer On the contrary, it predicts worse survival in pancreatic, ovarian and gastric cancers." (PMID 29342219, 2018). "eEF1A2 should be considered as a putative oncogene in breast cancer that may be a useful diagnostic marker and therapeutic target for a high proportion of breast tumours." (PMID 16156888, 2005). "Subsequently, Tomlinson and his research team made a significant discovery, finding a remarkable 30-fold increase in the levels of EEF1A2 mRNA in various types of breast cancer tissues in contrast to healthy breast tissue." (PMID 38172654, 2024). "We initially tested the possibility that an AKT-dependent mechanism determines the relationship between EEF1A1 and glycolysis based on earlier work showing that EEF1A2 overexpression activates AKT in human breast cancer cells." (PMID 38272231, 2024). "Like ovarian cancer, the 20q13.3 locus, which harbors the EEF1A2 gene, is frequently amplified in breast cancers." (PMID 38172654, 2024). "The 12 protein-coding genes upregulated in positive margin group included several well-known tumor markers for breast cancer (EEF1A2, EPHA6, FOXN4, SOX15)." (PMID 38038766, 2024). "The activation of Akt by eEF1A2 was previously supported by an overexpression study in pancreatic and breast cancer cells." (PMID 37051183, 2023). "Differently from our evidence, another study found that the overexpression of eEF1A2 protein was a predictor of good prognosis in breast cancer." (PMID 31220107, 2019). "In breast cancers, the overexpression of eEF1A2 is related with a positive prognosis in two studies." (PMID 31220107, 2019). "Cox regression assessed the association between eEF1A2 levels and disease-free survival (DFS) and breast cancer-specific survival (BCSS)." (PMID 31220107, 2019). "Overexpression of Isoform A2 of eukaryotic translation elongation factor (eEF1A2) played a contributory role in breast cancer progression." (PMID 29495357, 2018). "A single study has reported the regulation of EEF1α mRNA levels by EGF family of growth factors EEF1A2 mRNA levels are elevated in ERα+ breast cancers, indirectly indicating the involvement of estrogen signalling pathway in its transcriptional regulation." (PMID 29342219, 2018). "This gives rationale to a druggability of EEF1A2-dependent tumor growth in PCa with mTOR inhibitors, which are already in clinical use e.g. for metastatic renal cell carcinoma, breast cancer, neuroendocrine tumors and certain lymphomas." (PMID 28923030, 2017). "eEF1A2 has been shown to activate prosurvival Akt in a PI3K-dependent manner in a breast cancer cell line." (PMID 26981313, 2016). "In the BT549 human breast cancer cell line, eEF1A2 regulates cancer formation through Akt and PI3K-dependent remodeling of the cytoskeleton." (PMID 26981313, 2016). "Eukaryotic translation elongation factors 1 alpha, eEF1A1 and eEF1A2, are not only translation factors but also pleiotropic proteins that are highly expressed in human tumors, including breast cancer, ovarian cancer, and lung cancer." (PMID 25905039, 2015). "miR-744 was able to inhibit the proliferation of breast cancer cells by targeting eukaryotic translation elongation factor 1A2 (eEF1A2)." (PMID 24991193, 2014).
breast carcinoma (continued). "Previous studies showed that the expression levels of eEF1A2 are elevated and their genes (genomic region: 20q13) are amplified in a high proportion of solid tumors, such as ovarian and breast cancers." (PMID 35127825, 2021). "miR-663 and miR-744 have been found to negatively regulate eEF1A2 in breast cancer." (PMID 29495357, 2018). "Furthermore, there are data suggested that miR-744 exerts its tumor suppressor function by targeting proto-oncogene eEF1A2 or c-Myc, resulting in retardation of breast cancer cell or hepatocellular carcinoma cell proliferation." (PMID 25961434, 2015). "A model can be proposed whereby ZNF217 cooperates with Aurora-A, BCL2L1 or eEF1A2 in neoplastic progression of breast cancer through genomic co-amplification and/or through ZNF217-driven molecular regulation, which might amplify the impact of any genomic amplification." (PMID 26431164, 2015). "EEF1A2 and RPN2 are both located in 20q, and EEF1A2 has been suggested to be an oncogene and a diagnostic marker in various cancers, but has to our knowledge not previously been linked to sarcomas, whereas RPN2 has been shown to confer drug resistance in breast cancer." (PMID 23144859, 2012). "We therefore sought to establish whether eEF1A2 expression might be upregulated in breast cancer." (PMID 16156888, 2005). "Previous studies in human breast cancer cells using eEF1A2 overexpression experiments and siRNA, and HCC cells using eEF1A2 siRNA, have shown that eEF1A2 is a key activator of the prosurvival Akt." (PMID 37051183, 2023). "In this study, DRD2 was confirmed to suppress tumorigenesis if breast cancer through interacting with DDX5 and eEF1A2." (PMID 33859743, 2021). "In breast cancer cell line BT549, eEF1A2 expression stimulates cell migration and invasion in a largely PI3K and Akt-dependent manner, suggesting eEF1A2 regulates oncogenesis through Akt and PI3K-dependent cytoskeleton remodeling." (PMID 25905039, 2015). "In a large cohort of 438 primary breast cancer specimen, absence of EEF1A2 protein expression was a predictor of poor outcome." (PMID 28923030, 2017). "These processes are similar to those observed upon eEF1A2 over-expression in BT549 human breast cancer cells and non-transformed Rat2 cells." (PMID 26137586, 2015). "Two genes (EEF1A2 and PPIF) could similarly separate ER+, TAM-treated breast tumors by DMFS, and their protein levels were measured in an ER+ breast cancer cell line model with exogenous ERRγ." (PMID 25971350, 2015). "The expression of eEF1A2 is sufficient to stimulate the formation of filopodia in BT549 human breast cancer cells and non-transformed Rat2 cells." (PMID 25905039, 2015). "We therefore chose not to place any emphasis on the analysis of breast cancer cell lines as opposed to primary tumour samples since eEF1A2 expression seems to be a common property of transformed cells, rather than being specific for a tumour type." (PMID 16156888, 2005). "Although there is no direct evidence for an involvement of eEF1A2 in breast cancer, the genomic region to which EEF1A2 maps, 20q13, is frequently amplified in breast tumours." (PMID 16156888, 2005). "In a cancer-specific manner, EEF1A2 has been reported to promote specific pathways, for example, TGF-β/SMAD signaling in lung adenocarcinoma, the PI3K/AKT/mTOR pathway in hepatocellular carcinoma, the ERK pathway in breast cancer, and PI3K signaling in brain cancer." (PMID 38172654, 2024). "Analyzing EEF1A2 levels through immunohistochemistry on a breast cancer tissue microarray, they found that while normal breast tissue displayed minimal or no presence of EEF1A2 protein, strong and moderate EEF1A2 expression was evident in 11% and 48% of the tumor samples, respectively." (PMID 38172654, 2024). "ERRγ signaling is associated with poor DMFS in ER+, TAM-treated breast cancer, and ESRRG, EEF1A2, and PPIF comprise a 3-gene signaling node that may contribute to TAM resistance in the context of an active ERK/MAPK pathway." (PMID 25971350, 2015).
breast carcinoma (continued). "Recently, other studies have reported that the upregulation of eEF1A2 predicted a prolonged survival in ovarian and in HER2 negative breast cancer." (PMID 31220107, 2019).
ovarian carcinoma (37 papers, 1994 to 2025). A malignant neoplasm originating from the surface ovarian epithelium. "High doses of 50 and 100 mg/kg resveratrol inhibit the growth of ovarian cancer PA-1 cell xenograft tumours associated with reduced eEF1A2 expression." (PMID 38673959, 2024). "EEF1A2 overexpression has generally been associated with poorer prognosis in pancreatic ductal adenocarcinoma, non-small cell lung carcinoma, and ovarian cancer patients." (PMID 38172654, 2024). "EEF1A2 encodes an isoform of the alpha subunit of the elongation factor-1 complex and may be critical in the development of ovarian cancer." (PMID 34220510, 2021). "Dependence on EEF1A2 for resistance to apoptosis has also been documented in PA-1 ovarian cancer cells and SH-SY5Y neuroblastoma cells." (PMID 38172654, 2024). "Ectopic EEF1A2 expression enhanced the proliferative capacity of the SK-OV-3 ovarian carcinoma cell line." (PMID 38172654, 2024). "We have identified notable disparities in EEF1A2 expression across ovarian cancer, gastric cancer, and acute myeloid leukemia datasets derived from TCGA and individual reports." (PMID 38172654, 2024). "The case for EEF1A2 overexpression to be selectively associated with clear cell carcinoma histological subtype of ovarian cancer was further substantiated by a recent study showing EEF1A2 to be significantly overexpressed in ovarian clear cells." (PMID 38172654, 2024). "eEF1A2 was a eukaryotic elongation factor, and was reported as a potential oncogene in ovarian cancer." (PMID 33859743, 2021). "Eukaryotic translation elongation factor 1 α2 (EEF1A2) is an oncogene that promotes ovarian carcinogenesis and inhibits apoptosis of ovarian cancer cells." (PMID 33193718, 2020). "All together resveratrol down-regulates eEF1A2 in ovarian cancer cells and thereby favors apoptosis." (PMID 25905039, 2015). "When we examined expression of eEF1A2 by Western blotting in ovarian cancer cell lines we again found most cell lines to show high levels of expression." (PMID 17437010, 2007). "We wanted to establish the expression pattern of eEF1A2 in ovarian cancer of defined histological subtypes at both the RNA and protein level, and to establish the mechanism for the overexpression of eEF1A2 in tumours." (PMID 17437010, 2007). "Similar RT–PCR analysis of a panel of ovarian cancer cell lines shows most cell lines to overexpress eEF1A2 compared with a human leukaemic cell line (HL60), with levels as high as 70-fold higher in the most extreme instance (OVCAR5)." (PMID 17437010, 2007). "The tissue-specific translation elongation factor eEF1A2 is a potential oncogene that is overexpressed in human ovarian cancer." (PMID 17437010, 2007). "from normal DNA) in 12 of the 15 (80%) ovarian cancers expressing eEF1A2 at the RNA or protein level." (PMID 17437010, 2007). "The tissue-specific translation elongation factor eEF1A2 was recently shown to be a potential oncogene that is overexpressed in ovarian cancer." (PMID 16156888, 2005). "Additionally, in late-stage ovarian cancer, particularly in cases of serous endometrium cancer, the amplification of the 20q13 locus and EEF1A2 copy number further underscore its potential as a biomarker for assessing patient survivability." (PMID 38172654, 2024). "The role of EEF1A2 as a putative oncogene was first reported in 2002 in ovarian cancer." (PMID 38172654, 2024). "Altogether, these studies demonstrate that ZNF217 is a new oncogene that drives neoplastic progression in breast and ovarian cancers, and may act interdependently with eEF1A2." (PMID 26431164, 2015). "The enhanced expression of eEF1A2 protein in ovarian cancers correlates with poor prognosis." (PMID 25905039, 2015). "It was reported that human EEF1A2 promoted cell growth and proliferation in human ovarian cancer." (PMID 20505761, 2010).
ovarian carcinoma (continued). "Exceptionally, the TCGA dataset for ovarian cancer (TCGA–OV) showed a reduction in EEF1A2 and EEF1A1 expression compared with GTEx normal tissue, which could be due to other mutations, sample heterogeneity, normalization techniques or statistical methodologies, sample size, and clinical variations." (PMID 38172654, 2024). "The human example of this motif is located in the 2th intron of the gene EEF1A2 on the chromosome 20 (NCBI BLAST (version 2.2.25)), which is expressed in many tissues and is likely to be critical in the development of ovarian cancer." (PMID 33750298, 2021). "Oncomine analysis for ovarian cancer revealed significant difference of mRNA levels between tumor and normal samples, for EEF1A1, EEF1A2 and EEF1E1 only." (PMID 29342219, 2018). "Furthermore, the induced expression of eEF1A2 in NIH3T3 cells makes them tumorigenic and increases the growth rate of ES-2 ovarian carcinoma cells xenografted in nude mice." (PMID 25905039, 2015). "Finally, eEF1A2 silencing reversed resistance to apoptosis induced by ZNF217 overexpression, thus highlighting eEF1A2 as contributing towards the ZNF217-induced neoplastic properties of these precursor cells of ovarian carcinomas." (PMID 26431164, 2015). "The eEF1A2 gene is not expressed in normal ovary but highly expressed in ovarian cancer." (PMID 25905039, 2015).
pancreatic cancer (24 papers, 2013 to 2024). "In general, cancer development and aggressiveness of ovarian, breast, lung, gastric, hepatic and pancreatic cancers were associated with overexpression of eEF1A2." (PMID 31220107, 2019). "In pancreatic cancer tissues and cell lines, the downregulation of miR-663 inversely correlated with the upregulation of transcipts encoding eEF1A2." (PMID 29987196, 2018). "EEF1A2 was reported to facilitate the migration, invasion, and metastasis of pancreatic cancer cells by activating Akt and upregulating MMP-9 expression." (PMID 38957390, 2024). "The same study confirmed the increased levels of EEF1A2 expression at protein and mRNA levels in pancreatic cancer cell lines (Patu8988, BxPc-3, and Sw1990)." (PMID 38172654, 2024). "mRNA levels of EEF1A2 were also relatively higher in tissue from pancreatic cancer compared with normal tissue." (PMID 38172654, 2024). "siRNA knockdown of eukaryotic translation elongation factor 1 α2 (eEF1A2), a protein translation factor overexpressed in cancer cells, suppresses the migration and invasion of pancreatic cancer cells by downregulating MMP-9 and inactivating AKT." (PMID 35326412, 2022). "Eukaryotic protein translation elongation factor 1α2 (EEF1A2) is an oncogene that promotes the progression of breast and pancreatic cancer." (PMID 33473168, 2021). "MiR-663 was shown to decrease the proliferation and invasion potentials of pancreatic cancer cells both in vitro and in vivo by directly targeting eEF1A2." (PMID 29987196, 2018). "In pancreatic cancer EEF1A2 overexpression also resulted in an activation of AKT and led to an overexpression of the matrixmetallo-protease MMP9, which is a key player in extracellular matrix reorganization in context of cancer progression." (PMID 28923030, 2017). "The expression of eEF1A2 gene, located on chromosome 20q13 is significantly upregulated in pancreatic cancer." (PMID 25905039, 2015). "Although little or no eEF1A2 expression is present in normal pancreatic tissue, 83% of pancreatic cancers display increased expression of eEF1A2, suggesting that eEF1A2 plays an important role in pancreatic carcinogenesis." (PMID 25905039, 2015). "EEF1A2 overexpression increases cell proliferation in the SW1990 pancreatic cancer cell line." (PMID 38172654, 2024). "It attenuates tumor growth and invasiveness by targeting eEF1A2 in pancreatic cancer." (PMID 29566027, 2018). "In pancreatic cancer, the mRNA levels of EEF1A1, EEF1A2, EEF1B2, EEF1D and EEF1E1 were found to be significantly downregulated, as shown by Oncomine analysis." (PMID 29342219, 2018).